IL1B (interleukin 1 beta)
Diseases named in the same sentence as IL1B in open-access papers (continued):
Sharing a sentence is not in itself a finding about the gene and the disease.
atherosclerosis (continued). "The study of C-reactive protein (CRP), interleukin (IL)-1β, and NLR family pyrin domain-containing 3 (NLRP3) inflammasome has revealed critical roles for each in post-infarction systemic inflammation and progression of atherosclerosis." (PMID 34685553, 2021). "Under high glucose conditions, vascular endothelial cells produce high levels of proinflammatory cytokines, such as TNF-α and IL-1β, ROS (reactive oxygen species) and high levels of VCAM-1 and E-selectin, which initiate atherosclerosis via adhesion of circulating leukocytes to the endothelium." (PMID 34445477, 2021). "While it is well known that both IL‐1β and enhanced monocyte development exacerbate atherosclerosis, the role of IL‐1β in regulating myelopoiesis has not been well studied." (PMID 33204425, 2020). "Neutralization of IL-1α and IL-1β by induction of neutralizing antibodies resulted in reduced atherosclerosis in Nrf2+/+ApoE−/− but not in Nrf2−/−ApoE−/− mice." (PMID 32596261, 2020). "Vascular calcification derived from atherosclerosis and diabetes has been demonstrated to be a chronic inflammation event, which is regulated by inflammatory cytokines such as tumor necrosis factor (TNF)-α and interleukin (IL)-1β." (PMID 31938471, 2020). "Additionally, increasing IL-10, IL-4, IL-13, and TGF-β and reducing IL-1β, Il-6, TNF-α, CCL3, CCL4, and CCL5 can slow the progression of atherosclerosis." (PMID 32346605, 2020). "Moreover, ruxolitinib remarkably decreased plasma levels of IL-6, IL-1β, IFN-γ and TNF-α in rabbits with atherosclerosis." (PMID 32169038, 2020). "Similarly, Decitabine treatment downregulated the expression of inflammation genes, TNF-α, IL-6, and IL-1β, and the chemotaxis gene MCP-1 resulting in the amelioration of atherosclerosis." (PMID 32714333, 2020). "IL-1β, IL-6, and TNF-α are soluble low-molecular-weight-proteins that mediate crosstalk between immune and nonimmune cells and have been implicated in atherosclerosis development and progression." (PMID 32485823, 2020). "IL-1β, IL-6, IL-18, c-reactive protein (CPR), tumor necrosis factor α (TNF-α), etc., as important proinflammatory factors in the process of atherosclerosis, play an important role in promoting the formation of atherosclerosis." (PMID 32733941, 2020). "In the Atherosclerosis + Knockdown group, serum levels of TNF-α and IL-1β significantly decreased (P < 0.01), whereas the serum level of TGF-β1 significantly increased (P < 0.01), as compared with the Atherosclerosis + Vector group." (PMID 31781638, 2019). "LECT2 mitigated the expression and secretion of IL-1β, IL-8, TNF-α, and IL-1β dose-dependently in Apoe–/– mice fed with a Western diet, suggesting that LECT2 may inhibit atherosclerosis by alleviating inflammatory responses via Wnt/β-catenin signaling." (PMID 31310065, 2019). "Further studies in similar mouse models as well showed decreased severity of atherosclerosis in mice lacking NLRP3, caspase-1 or IL-1β, while in another study NLRP3 inflammasomes were not critically implicated in atherosclerosis progression." (PMID 31795299, 2019). "This leads to the release of an array of pro-inflammatory cytokines, such as interleukin-1-alpha (IL-1α), IL-1β, IL-6, tumor necrosis factor-alpha (TNF-α) and matrix metalloproteinases (MMPs), which further exacerbates atherosclerosis by promoting immune cell infiltration." (PMID 31357404, 2019). "Thus, the IL1B C allele may not be associated directly with IS per se, but could be modulating cytokines in the inflammatory processes that affect the development of atherosclerosis resulting in IS." (PMID 31480765, 2019). "In addition, individuals with arthritis have higher incidence of atherosclerosis and DGLA attenuated IL-1β stimulated proliferation of human adherent synovial cells, a hall mark of rheumatoid arthritis." (PMID 31202985, 2019). "IL-1β, IL-6, IL-8, and MCP-1 are important factors in the development of atherosclerosis." (PMID 31452653, 2019).
atherosclerosis (continued). "In the Atherosclerosis + Overexpression group, serum levels of TNF-α and IL-1β significantly increased (P < 0.01), whereas serum level of TGF-β1 significantly decreased (P < 0.05), as compared with the Atherosclerosis + Vector group." (PMID 31781638, 2019). "One study showed that the absence IL-1α significantly decreased atherosclerotic plaque area in a high-fat diet C57BL/6 mouse model, and the absence of IL-1β did not reduce atherosclerosis development in a statistically significant manner." (PMID 31354731, 2019). "Considering such negative effects of IL1B, the inhibition of its activity has become a potential therapeutic target in the prevention and treatment of atherosclerosis." (PMID 31780867, 2019). "Inflammatory signals involved in atherosclerosis, including cholesterol crystals, hypoxia, and turbulent flow, activate the NLRP3 inflammasome, which is a multi-protein assembly that integrates these signals and specifically activates the IL-1β isoform." (PMID 29922680, 2018). "A plethora of information, resulting from the analysis of rodent and human atherosclerotic plaques, has demonstrated that IL-1β and IL-18, both of which are products of the NLRP3 inflammasome activation, play a key role in the initiation and progression of atherosclerosis." (PMID 29515457, 2018). "Mice lacking NLRP3 inflammasome-related genes, e.g., NLRP3, ASC, and IL-1β, had markedly decreased atherosclerosis compared to wild-type mice in response to a high-cholesterol diet, indicating the important roles of the NLRP3 inflammasome in atherosclerosis." (PMID 30186288, 2018). "Unexpectedly, the fatty acids elicit release of IL-1α but not IL-1β, revealing a selective IL-1α-persistent pathway of vascular inflammation and pathology, and suggesting a role of IL-1α in atherosclerosis." (PMID 29329335, 2018). "Previous reports have demonstrated that TNFα or IL-1β knockout mice show an alleviation of atherosclerosis, without an improvement in serum lipid parameters." (PMID 28777298, 2017). "SAA has been widely considered not only as a biomarker of inflammation and atherosclerosis, but also as a proinflammatory mediator that could directly stimulate the production of series of cytokines, such as TNF-α, IL-1β, MCP-1, and Lp-PLA2." (PMID 27006946, 2016). "This study investigated whether IL-1α and IL-1β overlap in regulating the expression of MMP-3 and other remodeling-related proteases in isolated human cells relevant to atherosclerosis in primary culture and in fresh human carotid endarterectomy specimens." (PMID 27032103, 2016). "IL-1β, TNF-α, MCP-1 and MMP-2 can promote the progression of atherosclerosis." (PMID 24755612, 2014). "Studies in mouse models however, suggest a dual role for IL1B, wherein absence of IL-1B decreases the severity of atherosclerosis." (PMID 24736319, 2014). "IL-1β, IL-6 and TNF-α trigger atherogenesis by sensitizing vascular smooth muscle cells and inducing secretion of cellular adhesion molecules and matrix metalloproteinase (MMP) by monocytes during later stages of atherosclerosis." (PMID 20543948, 2010). "Protocatechuic acid dose-dependently inhibited the inflammation response, as evidenced by a reduction in IL-1β, IL-6, and TNF-α at the mRNA and protein levels in MLCs stimulated or unstimulated with 50 pg/mL of LPS, a reachable level in patients or laboratory animals with atherosclerosis." (PMID 40292571, 2025). "In the context of atherosclerosis, 4-HNE accumulates within vascular plaques, where it exacerbates inflammation through the upregulation of pro-inflammatory cytokines such as IL-8 and IL-1β, and may contribute to plaque destabilization and rupture." (PMID 41226332, 2025). "In addition, it did not showeffectiveness in reducing inflammation in patients with atherosclerosis—thelevels of IL-1β, IL-6 and CRP did not decrease." (PMID 40160593, 2025).
atherosclerosis (continued). "It should be also pointed out that as TRIM13 was induced by both WD and IL-1β in peritoneal macrophages and MASMCs affecting cholesterol efflux and oxLDL uptake, it is likely that both these cell types are contributing to TRIM13-mediated foam cell formation and atherosclerosis." (PMID 38537695, 2024). "Mechanistic studies have verified that AK136714 directly targets HuR (ELAVL1) to promote the mRNA stability of TNF-α and IL-1β and increases the transcription of Bim, indicating that AK136714 could function in atherosclerosis and provide potential novel drug targets for atherosclerosis intervention." (PMID 37418054, 2024). "PCA supplementation curtails IL-1β expression and NF-κB activation in lesions, inhibits the macrophage expression of IL-1b/IL-1β mRNA and protein, and initiates NF-κB activation through the upregulation of MERTK and MAPK 3/1, thereby lessening atherosclerosis severity." (PMID 39459158, 2024). "The levels of circulating pro-inflammatory cytokines, such as interleukin-1 beta (IL-1β), interleukin-6 (IL-6), and tumor necrosis factor-alpha (TNF-α), which are elevated in T2DM patients, underscore the relationship between T2DM and inflammation in the pathogenesis of atherosclerosis." (PMID 39125322, 2024). "Notably, the clinical use of canakinumab, an anti-IL-1β agent, has shown significant promise, as it reduced the incidence of lung cancer in patients with atherosclerosis, providing a robust clinical validation of the critical role of NLRP3 and IL-1β in cancer pathophysiology." (PMID 39301197, 2024). "Therefore, the activation of the IL-1β/IL-6 axis by 2-AG is an interesting novel finding in vitro, but it remains unlikely to be a driver of atherosclerosis in our mouse model." (PMID 36178662, 2023). "Inflammatory modulators/biomarkers, such as IL-1α, IL-1β, IL-6, IL-12, IL-15, IL-18, and tumor necrosis factor α, or alternative anti-inflammatory cytokine IL-10, and adhesion molecules (ICAM-1, VCAM-1), involved in atherosclerosis progression have been shown to predict cardiovascular diseases." (PMID 37374202, 2023). "However, although PCSK9-Il1a-/- animals show reduced IL-1β secretion, this does not appear to be the driving factor for atherosclerosis, because PCSK9-Il1b-/- animals do not show a reduction in plaque size." (PMID 37701434, 2023). "We also do not know how IL‐1β is activated at first place in the development of atherosclerosis." (PMID 36633253, 2023). "MONO are involved in vascular accumulation, upregulation of IL-1β, IL-6 and TNF-α expression in the brain, formation of reactive oxygen species (ROS), promotion of angiotensin-II (AngII) and other mechanisms that form atherosclerosis, brain injury, heart and kidney injury." (PMID 37265570, 2023). "The reason is that as a human monoclonal antibody targeting IL-1β, canakinumab might exert cardiovascular benefits by mediating the activation of IL-1β and the NLRP3 inflammasome within the kidney, thus contributing to cardioprotection during atherosclerosis." (PMID 37123477, 2023). "Accordingly, we propose that IL-1β secreted by inflammatory macrophage induces the functional alterations in macrophage-like VSMCs through downregulating STAT3, and this signaling cascade may play as a main driver in atherosclerosis progression." (PMID 36456628, 2022). "SARS-CoV-2 infection stimulates secretions of IL-1β, interferon-γ (IFN-γ), IFN-γ-induced protein 10kDa (IP-10), monocytic chemoattractant protein-1 (MCP-1), interleukin-4 (IL-4), IL-6, and interleukin-10 (IL-10), some of which can trigger a cytokine storm and atherosclerosis in a host." (PMID 36289895, 2022). "In conclusion, our study demonstrated that decreased expression of miR-24-3p and increased expression of miR-595 in patients with CAD may lead to progression of atherosclerosis plaque by regulating the expression of CCL3, CCL4, IL-1β, TNFαIP3, and NF-κBIα genes." (PMID 36381642, 2022).
atherosclerosis (continued). "Therefore, IL-1β has been considered as a key mediator of NLRP3 inflammasome and atherosclerosis." (PMID 36304814, 2022). "The negative effect of NLRP3 on atherosclerosis is mainly dependent on its effector cytokine IL-1β." (PMID 35647057, 2022). "On the basis of the evidence that NAD+ improved endothelial function after impairment by IL-1β in the isolated aorta, we further examined the effect of increasing NAD+ concentration in vivo against endothelial dysfunction and vascular inflammation in a mouse model of atherosclerosis in vivo." (PMID 35453391, 2022). "Similarly, in high-risk atherosclerosis patients with CKD, treatment with canakinumab, an IL-1β neutralising antibody, had no beneficial effect on kidney function, but significantly reduced major adverse cardiovascular events." (PMID 36030251, 2022). "However, inflammatory cytokines TNF-α, IL-1β, and IL-6 are important in atherosclerosis pathogenesis, as recently shown by the CANTOS trial, which found that specifically targeting inflammation (IL-1β inhibition) improves clinical outcomes in patients with a previous myocardial infarction." (PMID 32647892, 2021). "Excessive activation of the NLRP3 inflammasome and subsequent release of IL-1β have been shown to play a major role in the occurrence, development, and complications of atherosclerosis, acute myocardial infarction, non-ischemic injury to the myocardium, and heart failure." (PMID 34381021, 2021). "Humanin treatment also inhibits the high glucose-induced secretion of TNF-α and IL-1β and reduces the expression of VCAM-1 and E-selectin, thus preventing hyperglycaemia-induced attachment of the monocytes to the vascular cells, endothelial dysfunction and atherosclerosis progression." (PMID 34445477, 2021). "Inflammatory cytokines including interleukin-1beta (IL-1β), tumor necrosis factor alpha (TNF-α), transforming growth factor-beta (TGF-β), and interferon-gamma (IFN-γ) induce endothelial dysfunction and the acquisition of mesenchymal properties, therefore contributing to atherosclerosis." (PMID 34604359, 2021). "Nicotine induces the production of various inflammatory factors, such as interleukin-1β (IL-1β), nuclear factor-κβ, and necrosis factor-α, and NLRP3 inflammasome-mediated pyroptosis was recently considered to be an important pathogenicmechanism on atherosclerosis." (PMID 34490270, 2021). "The finding that pro-inflammatory cytokines such as interleukin (IL)-1β and tumor necrosis factor-α (TNF-α) could give rise to the expression of adhesion molecules and chemokines by ECs providing a support of the inflammatory basis of atherosclerosis." (PMID 35008500, 2021). "Meanwhile, growing evidences have confirmed that, some inflammatory cytokines, such as IL-10, IL-1β, IFN-γ and TNF-α, may be responsible for the pathogenesis of atherosclerosis because these cytokines can result in the adhesion of leukocytes to vascular endothelium and foam cell formation." (PMID 32169038, 2020). "On the other hand, the Cardiovascular Inflammation Reduction Trial indicated that low-dose methotrexate, an immune suppressant, did not decrease cardiovascular events in patients with stable atherosclerosis when it did not reduce the levels of IL-1β, IL-6, and C-reactive protein." (PMID 33227973, 2020). "Accordingly, lack of IL-1β decreases the severity of atherosclerosis in mice." (PMID 32384773, 2020). "In the same way, ApoE-/- mice subjected to atherosclerosis, showed a lack of IL-1β smaller lesions." (PMID 32545788, 2020). "Therefore, given the importance of IL‐1β in both RA and CVD, we hypothesised that IL‐1β signalling exacerbates atherosclerosis in RA." (PMID 33204425, 2020). "Compared with the oe-NC group, the levels of IL-1β and TNF-ɑ in the oe-CDKN2B-AS1 group were significantly decreased (p < 0.05), which ultimately suggested that CDKN2B-AS1 could inhibit the inflammatory response in atherosclerosis." (PMID 30926762, 2019).
atherosclerosis (continued). "Data linking IL-1β to atherosclerosis stem from early work demonstrated that a lack of IL-1β decreases the severity of atherosclerosis and that administration of a monoclonal antibody targeted against IL-1β limits the progression of atherosclerosis in ApoE deficient mice." (PMID 31357404, 2019). "However, numerous triggers involved in atherosclerosis, including cholesterol crystals, turbulent blood flow, and hypoxia, also activate the NLRP3 inflammasome, which integrates these and other signals to activate IL-1β." (PMID 30873416, 2019). "It is hypothesized that in IS development, IL1B is involved in thrombus formation rather than in atherosclerosis progression because IL1 induces tissue factor and plasminogen activator inhibitor type 1 gene expression." (PMID 31480765, 2019). "It has been recently reported that both IL-1β maturation and its release are tightly regulated by NLRP3 inflammasome, which has been involved in several systemic inflammatory diseases such as gout, atherosclerosis, pulmonary fibrosis and contact hypersensitivity." (PMID 29434227, 2018). "However, the overall effects of dapagliflozin on atherosclerosis in DM and the potential benefits involved, for example, their effects on IL-1β and IL-18 cytokines and NLRP3 inflammasome systems, have not been evaluated." (PMID 28104929, 2016). "Moreover, dapagliflozin inhibited the expression of NLRP3, ASC, caspase-1, IL-1β, and IL-18 in DM mice, and such expression was also decreased in the nondiabetic atherosclerosis model (not statistically significant)." (PMID 28104929, 2016). "IL-1β is involved in the onset of acute local or systemic inflammation and contributes to a variety of chronic noninfectious diseases, including ischemic injury, atherosclerosis, type 2 diabetes, and osteoarthritis." (PMID 25386048, 2014). "Levels of serum IL-1β and TNF-a dropped, mRNA and protein expression of E-sel, VCAM-1, ICAM-1 and MCP-1 in the aorta of rabbits were respectively down-regulated by the treatment of kaempferol, indicating that kaempferol can prevent atherosclerosis by alleviating vascular inflammation." (PMID 23895132, 2013). "Furthermore, studies in hypercholesterolemic mice suggest that lack of IL-1β or over-expression of IL1RA can partly protect against atherosclerosis." (PMID 20070880, 2010). "In addition, IL-1β levels have been shown to correlate with the number of diseased vessels strongly and significantly among subjects with CAD, thus, pro-inflammatory cytokines have a crucial role not only for atherosclerosis pathogenesis but for the extent of atherosclerotic CVD, as well." (PMID 36835838, 2023). "Our in vitro data also show that F. nucleatum promotes the secretion of inflammatory factors, such as TNF-α, IL-1β, IL-6, and the chemokine MCP-1 during foam cell formation, which suggests that the increased systemic inflammation level induced by F. nucleatum might accelerate atherosclerosis." (PMID 35359716, 2022). "IL-1β has not been studied as a biomarker for cardiovascular disease because unlike hsCRP and IL-6, it is difficult to directly measure its levels in the plasma; nevertheless, many studies have been conducted to examine its role as a therapeutic target in atherosclerosis." (PMID 34071276, 2021). "In addition, atherosclerosis is considered to be a chronic inflammatory disease of the large and medium arteries, with changes in pro-inflammatory cytokines such as tumor necrosis factor-alpha (TNF-α),interleukin (IL)-6, and IL-1β, and anti-inflammatory cytokines including IL-10." (PMID 32231564, 2020). "No significant changes in relation to the serum levels of IL-1β and TNF-ɑ in the M-oe-CDKN2B-AS1 + oe-ADAM10 group were detected, highlighting the inhibitory role of CDKN2B-AS1 in the stimulating effect of ADAM10 on the inflammatory response associated with atherosclerosis." (PMID 30926762, 2019).